DMRT1 (doublesex and mab-3 related transcription factor 1)
Description:
Transcription factor that plays a key role in male sex determination and differentiation by controlling testis development and male germ cell proliferation. Plays a central role in spermatogonia by inhibiting meiosis in undifferentiated spermatogonia and promoting mitosis, leading to spermatogonial development and allowing abundant and continuous production of sperm. Acts both as a transcription repressor and activator: prevents meiosis by restricting retinoic acid (RA)-dependent transcription and repressing STRA8 expression and promotes spermatogonial development by activating spermatogonial differentiation genes, such as SOHLH1. Also plays a key role in postnatal sex maintenance by maintaining testis determination and preventing feminization: represses transcription of female promoting genes such as FOXL2 and activates male-specific genes. May act as a tumor suppressor. May also play a minor role in oogenesis (By similarity).
Synonyms: DMT1; CT154
Tractability: PROTAC: its protein half-life has been measured.
Gene: Protein-coding gene on chromosome 9 (841,690 to 969,090, forward strand). Ensembl gene ENSG00000137090.
Subcellular location: Nucleus
Pathways (Reactome):
Developmental Biology: Transcriptional regulation of testis differentiation
Gene Ontology:
Molecular function: identical protein binding; sequence-specific double-stranded DNA binding; cis-regulatory region sequence-specific DNA binding; DNA-binding transcription factor activity, RNA polymerase II-specific; RNA polymerase II cis-regulatory region sequence-specific DNA binding; chromatin binding; DNA-binding transcription activator activity, RNA polymerase II-specific; double-stranded DNA binding; RNA polymerase II transcription regulatory region sequence-specific DNA binding; sequence-specific DNA binding
Biological process: male germ cell proliferation; male sex determination; male sex differentiation; negative regulation of meiotic nuclear division; negative regulation of transcription by RNA polymerase II; positive regulation of mitotic nuclear division; positive regulation of transcription by RNA polymerase II; regulation of transcription by RNA polymerase II; Sertoli cell differentiation; sex differentiation; intracellular signal transduction; regulation of DNA-templated transcription
Cellular component: nucleus; chromatin; cytoplasm
Genetic constraint (gnomAD): Loss-of-function variants: 7 observed, 30.46 expected, observed/expected ratio (o/e) 0.23, 90% interval 0.13 to 0.43. The synonymous counts are far from expectation, so gnomAD's model fits this gene poorly and the ratio says little. Missense variants: 625 observed, 484.96 expected, observed/expected ratio (o/e) 1.29, 90% interval 1.21 to 1.38. Synonymous variants: 278 observed, 201.27 expected, observed/expected ratio (o/e) 1.38, 90% interval 1.25 to 1.52.
Gene-disease validity (ClinGen):
ClinGen rates the evidence that DMRT1 causes each of these diseases.
spermatogenic failure (autosomal dominant): Definitive. A male infertility characterized by dirsuption of the process of sperm development from diploid cells into mature haploid spermatozoa.
Homologues: Orthologues: chimpanzee DMRT1 (99% identical), dog DMRT1 (88% identical), pig DMRT1 (86% identical), guinea pig DMRT1 (83% identical), mouse Dmrt1 (83% identical), rat Dmrt1 (82% identical), tropical clawed frog kank1 (61% identical), zebrafish dmrt1 (35% identical), Caenorhabditis elegans dmd-7 (15% identical), Caenorhabditis elegans dmd-9 (11% identical). Paralogues in human: DMRT3 (26% identical), DMRTA2 (26% identical), DMRT2 (25% identical), DMRTA1 (25% identical), DMRTC2 (20% identical), DMRTB1 (18% identical), DMRTC1 (8% identical), DMRTC1B (8% identical).